IL10 (interleukin 10)
Diseases named in the same sentence as IL10 in open-access papers (continued):
Sharing a sentence is not in itself a finding about the gene and the disease.
chronic fatigue syndrome (7 papers, 2015 to 2025). "Other fatigue syndromes, such as myalgic encephalomyelitis (chronic fatigue syndrome) and cytokine release syndrome, are also associated with increased activated T-lymphocytes and pro-inflammatory cytokines such as IL-6, IL-10, and IFN-γ." (PMID 40952384, 2025). "Notably, a previous study examining CSF cytokine profiles in a group of 18 patients with chronic fatigue syndrome found that IL-10 levels were significantly reduced." (PMID 36140159, 2022). "In addition to this, LPS can also modulate the production of the anti-inflammatory cytokine IL-10 and measuring LPS-induced IL-10 response has been shown to be a sensitive marker for disturbed glucocorticoid regulation at least in patients with chronic fatigue syndrome." (PMID 33447872, 2021). "Other studies reported increased gene expression of IL-10, but not IL-6 or TNF, up to 48 h after a 25-min cycling exercise in FMS comorbid with chronic fatigue syndrome, but no change in patients with FMS only." (PMID 27296860, 2016).
chronic gastritis (7 papers, 2012 to 2020). Inflammation of the stomach that is chronic in nature. "According to activity of the chronic gastritis, there was decreased IL-10 expression in H. pylori-infected with moderate/intense activity (HP2/3) compared with that in the control (non-infected, with no activity or low activity)." (PMID 33013895, 2020). "H. pylori-infected patients with chronic gastritis carrying the GCC haplotype exhibited higher IL-10 mucosal expression levels than ATA carriers and this correlated with a higher prevalence of virulent cagA+/vacAs1+ /babA2+ H pylori strains." (PMID 31092242, 2019). "The expression of cytokines IL-23, IL-21, TNF-α, and IL-10 did not have a significant association with the severity of chronic gastritis in this study." (PMID 29391865, 2017). "IL-10 knockout mice infected with Helicobacter felis demonstrate that a lack of IL-10 causes severe chronic gastritis and substantially enhances the Helicobacter-specific Th1 immune response." (PMID 22526791, 2012). "Expression of serum cytokines (IL-17A, IL-21, IL-23, IL-10, and TNF-α) in H. pylori-infected patients was compared with healthy controls and correlated with disease severity (mild chronic gastritis, moderate chronic gastritis, and severe chronic gastritis)." (PMID 29391865, 2017). "Infection of IL-10-/- mice, lacking IL-10 expression, with H. pylori and H. felis elicited a more severe chronic gastritis compared with that seen in wild-type mice, which even led to spontaneous eradication of Helicobacter infection." (PMID 26115373, 2015).
chronic hepatitis (7 papers, 2013 to 2024). An active inflammatory process affecting the liver for more than six months. "IL-10 was significantly higher in patients with chronic hepatitis (B, C, or both) than in healthy controls." (PMID 36674897, 2023). "In the present study, we observed higher intrahepatic IL10 mRNA expression levels in the control group than in the group with chronic hepatitis." (PMID 33125400, 2020). "This fusion protein exhibited the induction of anti-inflammatory molecules, such as IL-10, IL-1Ra, and PD-1, in RAW264.7 cells, or hepatoprotective effects on carbon tetrachloride-induced chronic hepatitis mice." (PMID 38399475, 2024). "One of the previous studies has shown decreased levels of IL-10 in the healthy group compared to the chronic hepatitis group, which is not in correlation with our results." (PMID 37569857, 2023).
chronic pancreatitis (7 papers, 2009 to 2022). A chronic inflammatory process causing damage and fibrosis of the pancreatic parenchyma. "The study identified high levels of IL-6 in PDAC cases compared to chronic pancreatitis patients and elevated IL-10 and TNFα in PDAC cases compared to healthy subjects." (PMID 24884871, 2014). "In fact, the nociceptive status of chronic pancreatitis patients correlated with pancreatic pituitary adenylate cyclase-activating polypeptide levels and with IL-10 bias of pituitary adenylate cyclase-activating polypeptide-exposed peripheral blood mononuclear cells of chronic pancreatitis patients." (PMID 20049222, 2009). "It has been observed in several experimental models that IL-4 could modulate the regulation of complement activation or the generation of IL-10 in chronic pancreatitis." (PMID 19646232, 2009). "Similarly, IL-10 KO mice have an increased degree of inflammation and fibrosis in chronic pancreatitis; however, this study was performed on an IL-10 KO background, and the role of BM-secreted IL-10 in pancreatic fibrosis is not well explored." (PMID 27314021, 2016).
cutaneous T-cell lymphoma (7 papers, 2020 to 2025). "Beyond cytotoxicity, they reduce IL-10 secretion via STAT3 inhibition in cutaneous T-cell lymphoma and, in renal cancer models, decrease myeloid-derived suppressor cells while enhancing PD-1 blockade efficacy." (PMID 41296440, 2025). "In this way, tolerogenic DC induces T-cell anergy and induction of tolerogenic cytokines (IL-10), i.e., a phenotype resembling that of DC in cutaneous T-cell lymphoma (CTCL)." (PMID 38534347, 2024). "Work from our collaborators demonstrated that GaM decreased the expression of pro-angiogenic cytokine IL-10 in a mouse model of cutaneous T-cell lymphoma, whereas angiostatic proteins CXCL10 and CXCL11 were significantly upregulated." (PMID 38288102, 2023). "In a mouse model study, M2 macrophages can increase the secretion of IL-10 by macrophages which is necessary for the maximum growth of human cutaneous T-cell lymphoma." (PMID 33154947, 2020). "The results are consistent with the previous study regarding cutaneous T cell lymphoma, stating that TGF-β and IL-10 are hallmarks of advanced stages, increased cell migration, and decreased antitumor responses." (PMID 33767152, 2021). "The decrease in the IL-10 level in our study may also be stimulated by BTZ, as it was previously found in cutaneous T-cell lymphoma cells." (PMID 38835345, 2024).
cysticercosis (7 papers, 2011 to 2024). "Positive cysticercosis status was significantly associated with a decrease in IL-10 levels (β = -0.419, p = 0.022), while IL-5 levels were significantly increased (β = 0.229, p = 0.035)." (PMID 39093864, 2024). "In summary, increased IL-10 secretion may inhibit the host’s immune responses against cysticercosis, leading to a persistent infection." (PMID 34540719, 2021). "In human neurocysticercosis, asymptomatic patients usually present elevated levels of IL-10, suggesting that IL-10 might play a role in disease outcome." (PMID 25811778, 2015). "IL-10 and/or TGF-β1 were also detected in brains of individuals with neurocysticercosis or neurotoxocarosis, but their cellular source was not identified." (PMID 27842570, 2016). "In early stages of experimental cysticercosis a clear but transient Th1-type immune response develops (high levels of IL-2 and IFN-γ), but as infection time progresses a permanent Th2-type response follows (high levels of IL-4, IL-6 and IL-10)." (PMID 21912714, 2011). "The immunopathology of T. crassiceps cysticercosis in mice is that of an initial non-permissive Th1 type, which shifts to a parasite permissive Th2 type during chronic stage of infection and is accompanied by an increase in IL-4, IL-6 and IL-10 cytokines." (PMID 22206032, 2011).
diabetic neuropathy (7 papers, 2015 to 2025). A chronic, pathological complication associated with diabetes mellitus, where nerve damages are incurred due to diabetic microvascular injury involving small blood vessels that supply these nerves, resulting in peripheral and/or autonomic nerve dysfunction. "IL-10 −1082 G/G polymorphism has also been found to be associated with the susceptibility to diabetic neuropathy in Indian population." (PMID 30873205, 2019). "On the other hand, it has also been reported an association between diabetic neuropathy and a single nucleotide polymorphism in the IL-10 gene that results in higher production of this cytokine." (PMID 28841856, 2017). "Minocycline, a drug with anti-inflammatory and immunomodulatory effects, has been found to cause IL-10 to increase in parallel with the decrease of proinflammatory cytokines in a mice model of diabetic neuropathy." (PMID 25961054, 2015). "Enhancing IL-10 signaling in this context has been proposed as a strategy to alleviate painful diabetic neuropathy (PDN), highlighting the cytokine’s potential in managing chronic complications." (PMID 40804870, 2025).
Down syndrome (7 papers, 2011 to 2025). "The biomarkers most frequently analyzed in studies of Down syndrome were IL-10, TNF-alpha, IL-1 beta, IL-4, IFN-gamma, and the genes STAT1, STAT3, and SOCS3, all of which are involved in the regulation of the immune response and periodontal inflammation." (PMID 41462866, 2025). "The levels of IFNγ, TNFα, IL-10 in the Down syndrome group (DS) were higher than in the intellectual Disabilities (ID) group (p < 0.05)." (PMID 21496308, 2011).
edema (7 papers, 2020 to 2026). An abnormal accumulation of fluid beneath the skin, or in one or more cavities of the body. "IL-36 administration exacerbated pulmonary edema, inflammatory cytokine levels (IL-10,TNF-α,MPO) and histopathological injury." (PMID 42103804, 2026). "Moreover, the carrageenan-induced paw oedema model in rats showed that pregabalin also increases the levels of antinociceptive IL-10." (PMID 35056145, 2022). "Methotrexate administration resulted in increased levels of TNF-α, MPO, GATA3, caspase-3, and pulmonary edema indices, while reducing the levels of TAC, SOD, Gpx, IL-10, T-bet, and FOXP3." (PMID 38245672, 2024).
Headache (7 papers, 2021 to 2023). Cephalgia, or pain sensed in various parts of the head, not confined to the area of distribution of any nerve. "Higher levels of IL-10 were associated with a more intense innate immune response and headache." (PMID 35625737, 2022). "For example, headaches are associated with elevated Tumor Necrosis Factor-α (TNF-α), Interleukin-10 (IL-10), Interleukin-1β (IL-1β), Interleukin-6 (IL-6), and Interferon-α (IFN-α) levels." (PMID 35053845, 2022). "Serum NLRP3 levels were correlated with headache duration and hospital stay, while headache response to paracetamol was negatively correlated with HMGB1 and positively associated with IL-10 levels." (PMID 34384355, 2021). "NLRP3 was correlated with headache duration and hospital stay, while paracetamol response was negatively associated with HMGB1 levels and positively correlated with IL-10 levels." (PMID 34384355, 2021). "The main finding of our study was that IL-10 levels were significantly higher in patients with headache while other interleukins, such as IL-23 and PIGF1, also showed a trend to be higher in this group." (PMID 34088273, 2021). "The higher levels of IL-10 -an anti-inflammatory cytokine- found in our sample in patients with headache may be explained as a counteract of cytokine release, reflecting a more intense immune response in these patients." (PMID 34088273, 2021). "However, the higher levels of the anti-inflammatory cytokine IL10 found in our sample in patients with headache may be interpreted as a response to proinflammatory cytokine storm, reflecting a more efficient immune response in these patients." (PMID 34088273, 2021). "Regarding the central tendency measures, in the comparison of the crude median values of cytokines, we observed that patients with headache had higher median values of GROa, IFN-gamma, IL-10, IL-13, IL-15, IL-17a, IL-21, IL-22, IL-27 and IL-6." (PMID 34088273, 2021). "IL-10, IL-23, and PIGF1 levels were significantly higher in patients with headache than in COVID-19 patients without headaches." (PMID 35911910, 2022).
Kawasaki disease (7 papers, 2018 to 2025). A rare inflammatory disease characterized by an acute febrile, systemic, self-limiting, medium-vessel vasculitis primarily affecting children. "In Kawasaki disease, there is evidence of imbalanced Th1/Th2 cell responses, and the plasma level and mRNA expression levels of Th1 cytokines (IFN-γ, IL-2) and Th2 cytokines (IL-4 and IL-10) are markedly elevated during the acute stage of Kawasaki disease." (PMID 37841239, 2023). "Alteration in serum expression of Transforming Growth Factor-beta (TGF-β) and IL-10 have been suggested to play a role in the pathogenesis of Kawasaki Disease (KD)." (PMID 31908741, 2019). "A comprehensive search was performed in MEDLINE and SCOPUS using the keywords of interleukin 10, transforming growth factor beta, and Kawasaki disease." (PMID 31908741, 2019).
keratoconus (7 papers, 2011 to 2025). A degenerative, structural disorder of the eye, characterized by a cone-shaped protrusion of the cornea. "Given IL-10’s primarily role as an anti-inflammatory cytokine, it testifies the complex imbalance of proinflammatory and anti-inflammatory factors in keratoconus." (PMID 40980981, 2025). "Others have examined isolated cytokines by conventional sandwich ELISA and reported concentrations of IL-6, TNF-α and IL-10 in control and keratoconus subjects." (PMID 21298010, 2011). "In the current study, we have determined the associations between nine mediators (IL-6, IL-10, CXCL8/IL-8, CCL5/RANTES, MMP-9, MMP-13, TIMP-1, t-PA, and PAI-1) in the tear fluid of keratoconic patients covering the whole spectrum of the disease (from subclinical to manifest keratoconus)." (PMID 26881061, 2016). "We observed significantly higher levels of IL-1β, IL-10, IFN-γ and TNF-α in moderate and severe keratoconus than in mild keratoconus (p < 0.05)." (PMID 38256126, 2024). "To address this controversial issue at the single-cell level, we first surveyed the predominant source of several reported cytokines increased in keratoconus samples, including IL1, IL6, IL10, TNF-α and TGF-β37,75,76." (PMID 35821117, 2022). "The means of IFN gamma, IL-10, IL-1 beta, IL-4, IL-6, and TNF alpha had a significant difference between the keratoconus patients and the normal subjects." (PMID 30245588, 2018). "Our aim was to determine the concentration of IL-4, IL-6, IL-10, RANTES, IFN gamma, and TNF alpha in the tear film of patients with keratoconus and their first degree family members." (PMID 30245588, 2018). "Interestingly, we observed a significantly higher level of IL-1β, IL-10, IFN-γ, and TNF-α with moderate and severe keratoconus than with mild keratoconus." (PMID 38256126, 2024). "Several studies have shown that there was no obvious change in IL-10 in tears of keratoconus and control subjects, while a few studies have suggested that there was reduced IL-10 in epithelium of KC patients." (PMID 36051483, 2022). "Interleukin (IL)-1β, IL-4, IL-6, IL-10, IL-12, IL-13, IL-17, interferon (IFN)-γ, chemokine C-C motif ligand 5 (CCL5) and tumor necrosis factor (TNF)-α were tested in tear samples and sera of keratoconus and control individuals by multiplex immuno-bead assays." (PMID 21298010, 2011). "By correlating corneal and immunological data, we observed significantly higher levels of IL-1β, IL-10, IFN-γ and TNF-α in moderate and severe keratoconus than in mild keratoconus (p < 0.05), but not exceeding the values in the control group." (PMID 38256126, 2024).
Klebsiella pneumonia (7 papers, 2012 to 2024). An pneumonia caused by infection with Klebsiella. "For instance, germ-free mice infected with Klebsiella pneumonia were more susceptible to bacterial infection in an IL-10-dependent manner." (PMID 37996951, 2023). "High levels of IL-10 may increase the risk of infections by Listeria monocytogenes, Klebsiella pneumonia, and Streptococcus pneumonia." (PMID 38248028, 2024). "Besides, administrating L. plantarum CIRM653 upregulated the IL-10 level in rats infected with Klebsiella pneumonia." (PMID 33828554, 2021). "Analysis of cytokine responses of respiratory leukocytes after stimulation with Klebsiella pneumonia indicated reduced IFN-γ and TNF-α expression and increased IL-10 and IL-12p70 production after 7 day low dose skin TLR7 triggering." (PMID 22927956, 2012).
Lewis lung carcinoma (7 papers, 2016 to 2021). "In this study, we explored the efficacy of combining IL-10 and the oncolytic Ad-hTERT viroimmunotherapy in Lewis lung carcinoma (LLC) and B16F10-bearing C57BL/6 mice and found that the combination therapy demonstrated a profound antitumor effect." (PMID 33717103, 2021). "In a murine model of Lewis lung carcinoma-derived MPE, IL-10 deficiency led to increased γδ T cell intrapleural proliferation and IL-17a production, reduced MPE volume, and longer survival that was dependent on γδ T cells." (PMID 33013860, 2020). "Analysis of Lewis lung carcinoma cells implanted in syngeneic recipient mice resulted in increased IL-10 (Interleukin 10) secretion by Treg cells and tumor expansion due to PTEN downregulation mediated by miR-214." (PMID 31952362, 2020). "Transgenic mice overexpressing IL-10 developed larger tumors than control mice when injected with Lewis lung carcinoma cells, suggesting that the production of IL-10 prevents a full immune response against the tumor cells." (PMID 27375834, 2016). "Coculture experiments with Lewis lung carcinoma (LLC) cells showed that glufosinate impaired the effect of murine IL10 macrophages on LLC proliferation and migration (Fig EV2C and D), although the concentrations of glufosinate used did not exert any differential effect." (PMID 32885605, 2020). "Lewis lung carcinoma (LLC) and B16F10 tumor-bearing immunocompetent C57BL/6 mice that received Ad-hTERT or IL-10 alone showed mild antitumor effect, while the combination therapy shrink tumor bulks and prolonged survival remarkably." (PMID 33717103, 2021). "Also, ELISA was used to test the exposure levels of HMGB1, IL-10, and TGF-β under different “time windows” and “dose windows” of irradiation with X-rays and carbon ions for A549, H520, and Lewis Lung Carcinoma (LLC) cell lines." (PMID 33968889, 2021).
lupus erythematosus (7 papers, 2012 to 2024). An autoimmune, connective tissue chronic inflammatory disorder affecting the skin, joints, kidneys, lungs, heart, and the peripheral blood cells. "In addition, rs573775T* allele was regarded as a risk factor for lupus erythematosus in carriers of the high IL-10 producer genotype." (PMID 34661876, 2022). "In mice, the lupus erythematosus model after vancomycin administration, treatment with gut microbiota DNA solution, administered orally, promoted IL-10 and Bregs population." (PMID 36618354, 2022). "Compared to the control with vancomycin administration, the Breg population was bigger, the IL-10 level was higher, and the onset of lupus erythematosus appeared later." (PMID 36618354, 2022).
mantle cell lymphoma (7 papers, 2014 to 2025). Mantle cell lymphoma is a rare form of malignant non-Hodgkin lymphoma affecting B lymphocytes in the lymph nodes in a region called the ``mantle zone''. "Variations in the interleukin-10 and tumor necrosis factor genes plus a family history of hematologic malignancies have all been proposed as a potential risk factors for developing mantle cell lymphoma." (PMID 40843808, 2025). "In mantle cell lymphoma, B cell-derived CCL3 forms a positive feedback loop with M2 macrophages: CCL3 promotes M2 polarization, and M2 macrophages secrete IL-10 to further stimulate CCL3 secretion by MCL cells, accelerating tumor growth." (PMID 41246318, 2025). "In mantle cell lymphoma (MCL), primary MCL cells transform monocytes into specific CD163+ M2-like macrophages by secreting CSF1 and IL-10." (PMID 32801364, 2020). "TLR4 signaling in human mantle cell lymphoma cells inhibited T cell proliferation and CTL-induced cytolysis, and this effect was partially restored by neutralization of IL-10 and/or VEGF." (PMID 28881826, 2017). "LPS-pretreated TLR4-positive/myeloid differentiation 88 (MyD88)-positive mantle cell lymphoma(MCL) inhibited the proliferation and cytolytic activity of T cells by secreted IL-10 and VEGF, and triggers a cascade that leads to MCL growth and evasion from immune surveillance." (PMID 25299052, 2014).